KRAS (KRas proto-oncogene, GTPase)
Diseases named in the same sentence as KRAS in open-access papers (continued):
Sharing a sentence is not in itself a finding about the gene and the disease.
tumor (continued). "Other miRNAs have been shown to behave like KRAS tumor suppressors, in particular miRNA-181a in oral squamous cell carcinoma, and finally miRNA-30b in CRC." (PMID 29534749, 2018). "KYA1797K suppressed the growth of tumor xenografts induced by CRC cells as well as tumor organoids derived from CRC patients having both APC and KRAS mutations." (PMID 30459318, 2018). "KRAS mutations were detected in a fraction of FAP neoplasms and were significantly correlated with IME in FAP neoplasms, as observed in sporadic CRC." (PMID 30220972, 2018). "It has been shown that ALK-positive patients have higher levels of vascular endothelial growth factor-A (VEGF-A) and tumor vessel formations compared to EGFR and KRAS mutated NSCLC." (PMID 29318404, 2018). "A mutation in any of these 3 codons was found in the ctDNA of 12/28 patients (43%) with KRAS mutant tumours." (PMID 29362371, 2018). "Here, we found that the frequency of KRAS and BRAF mutations was higher in the lung metastatic tumours than that in the liver metastatic tumours." (PMID 30171333, 2018). "The results were correlated with tumor characteristics including EGFR expression, KRAS mutation, and CRT response based on the pathologic tumor regression grade (TRG)." (PMID 30186857, 2018). "While our single agent screen of GSK525762 revealed MM as a highly sensitive tumor type, the KRAS mutant cell line RPMI-8226 is one of the least responsive MM models to BET single agent treatment." (PMID 29674704, 2018). "They found that KRAS and BRAF are mutually exclusive in earlier tumor stages (Tis and T1), but concomitant mutations were detectable in higher tumor stages and correlated with increased depth of invasion." (PMID 30234115, 2018). "Bromodomain and Extra-Terminal (BET) protein inhibition has displayed anti-tumor activity in a wide range of cancers, including KRAS-driven malignancies." (PMID 29721157, 2018). "These tumours also exhibited a decrease in KRAS, NAP1L1, and ETS1 expression in 786-O/miR-532-5p cells, as assessed by IHC." (PMID 30082686, 2018). "MiR-30c and miR-21 enhanced cell proliferation and migration/invasion and inhibited apoptosis by targeting important tumor suppressor genes, inducing the activation of KRAS downstream pathways." (PMID 29440633, 2018). "Taken together, we found that pharmacological inhibition and gene silencing of GSK3α/β selectively induced apoptosis and inhibited tumor growth of mutant KRas-dependent tumors, which was at least in part mediated by c-Myc and β-catenin." (PMID 30514931, 2018). "One half of each preserved tumor was analyzed by RFLP to determine the wild-type to mutant KRAS mRNA transcript ratio." (PMID 29851957, 2018). "Consistent with this, a mouse model with codon optimised KRAS genes generated fewer urethane-induced tumours than unaltered controls." (PMID 30287508, 2018).
tumor (continued). "Our results suggest this combination renders a highly synergistic anti-tumor effect at specific dose ranges in RICTOR/KRAS-altered NSCLC cells, both in vitro and in vivo." (PMID 30338041, 2018). "Studies in models of NSCLC have shown that radiotherapy stimulates PD-L1 expression on KRAS-mutant tumor cells and synergizes with anti-PD-1 agent to induce regression of KRAS-driven genetically engineered mouse models of NSCLC." (PMID 30060526, 2018). "This tumor-derived DNA can be extracted from plasma and used to detect BRAF proto-oncogene, KRAS, and serine/threonine kinase V600E mutations." (PMID 29728089, 2018). "In selected patients, a microdissection analysis of the adenomatous and squamous components present in each tumor was performed, showing that both exhibit the same EGFR or KRAS mutations." (PMID 30060526, 2018). "Molecular alterations including KRAS mutations, EGFR mutations, and ALK/ROS1 re-arrangements were detected in 23.2%, 19.6%, and 5.4% of analyzed tumor samples, respectively." (PMID 29707129, 2018). "The genetic profile of HT-29 cells represents the KRAS and NRAS wild-type tumor subtype, but includes the activating V600E mutation in the BRAF gene." (PMID 30410004, 2018). "The effectiveness and potential application of this compound in patients are demonstrated by the reduction in these proteins and the suppression of growth in tumor organoids derived from CRC patient tissues harboring both APC and KRAS mutations." (PMID 30459318, 2018). "The biomarker analysis set for predictive genomic markers (KRAS, NRAS, BRAF, or PIK3CA mutations) included 46 subjects with tumour tissue sequenced." (PMID 30425349, 2018). "We analyzed 14 biomarkers and 17 SNPs in prediagnostic blood and determined KRAS and BRAF mutation status in tumor tissue." (PMID 29694444, 2018). "Since KRAS represents a reliable tumor burden surrogate for PDAC (seen in close to 95% of PDAC) it was decided to perform ultrasensitive droplet digital PCR (ddPCR) in the complete series of 15 blood based liquid biopsies." (PMID 29599906, 2018). "Presence of KRAS, PIK3CA, and BRAF mutations was tested in cfDNA and tumor tissue with an overall concordance rate of 76% for KRAS, 88% for PIK3CA, and 97% for BRAF mutations." (PMID 29441349, 2018). "KRAS mutation affects the prognosis of ICC patients undergoing surgical resection and is associated with tumor glucose uptake." (PMID 29642912, 2018). "Since ctDNA KRAS had a concordance of 81.25% compared with tumor tissue in our study, we further aimed to analyze the prognostic role of ctDNA gene mutation status in subsequent first-line palliative chemotherapy." (PMID 29707525, 2018). "The recent development of circulating tumor DNA tests, or liquid biopsies, for the detection of KRAS mutants has shown variable concordance rates." (PMID 30519549, 2018). "Further, we do cite Sacher et al3 which describes the successful validation of the PrimePCR endothelial growth factor receptor gene (EGFR) and KRAS assays on circulating tumour DNA (ctDNA) against matched tumour specimens." (PMID 29346455, 2018). "KRAS exon 3 mutation was more likely to appear in lower TNM stage (P = 0.011) and smaller/less invasive tumor (P = 0.001) patients." (PMID 29666387, 2018). "Our present findings expand the paradigm of how mutant KRAS impacts tumor–host interactions: it renders tumor cells capable of sensing inflammatory IL-1β signals originating from the CCL2-recruited monocytes." (PMID 29445180, 2018).
tumor (continued). "In this manuscript, we revealed that human tumors dependent on mutant KRas require GSK3α/β for viability, survival, and tumor growth." (PMID 30514931, 2018). "KRAS exon 3 mutations seemed to confer a less aggressive biological behavior, because they were associated with lower TNM stage and smaller/less invasive tumor." (PMID 29666387, 2018). "In line with our previous findings, postoperative osteopontin serum levels were unaltered between patients with moderately (G2) or poorly (G3) differentiated tumours, left- or right-sided primary CRC and KRAS mutated or wildtype CRC." (PMID 30373147, 2018). "In vitro and in vivo studies revealed that G9a represses a gene signature highly associated with mutant KRAS-regulating and ECM-regulating genes, including Mmp10, which partially mediates the tumorigenicity of G9a-depleted tumor cells." (PMID 30455465, 2018). "An important finding of our studies is that suppression of GSK3α/β inhibits mutant KRas-dependent tumor growth at least in part by a c-Myc- and β-catenin-dependent mechanism." (PMID 30514931, 2018). "First, we addressed the question if the inhibited tumor cell proliferation observed after KRAS-esiRNA-treatment of human CRC xenografts is also the cause for decreased tumor growth in cetuximab-antibody-coupled PIK3CA-esiRNA (C-PIK3CA-esiRNA) treatment." (PMID 30001368, 2018). "In four cases, tumours were wild type in primary sites, but were RAS mutant type in lung metastatic sites; in another 1 case, gene mutation changed from KRAS G12D and PIK3CA E545A in primary site to wild type in lung metastatic site." (PMID 30171333, 2018). "With tumor progression, clonal aberrations appeared among KRAS and CDKN2A, as well as genes related to SWI/SNF mediated chromatin remodeling." (PMID 29599906, 2018). "The two cases who showed the primary tumours with KRAS wild type and the corresponding ovarian metastasis with KRAS G12S or G12V did not received any anti-EGFR antibody before oophorectomies." (PMID 29662660, 2018). "We conclude that the decreased tumor growth observed in the treatment groups is indeed based on the efficient downregulation of the intended and oncogenic factors KRAS and PIK3CA driven by an antibody-directed esiRNA delivery." (PMID 30001368, 2018). "In the conditional KRAS mutant mouse model, the expression of tumor‐driving mutant depends on viral Cre application, leading to a widespread, but not overall, initiation of tumor nodule formation." (PMID 30220105, 2018). "Intriguingly, in an animal model of KRAS driven neoplasia, NRA5A2 function constrains tumor initiation." (PMID 29544460, 2018). "According to recent reports, patients with a MSS/KRAS mutant tumor had the worst survival than the other three groups." (PMID 29423347, 2018). "Overall, KYA1797K effectively suppressed the formation and growth of tumor-derived organoids from CRC patients and overcame the insensitivity to cetuximab attributed to KRAS mutations by reducing the protein levels via degradation." (PMID 30459318, 2018). "Nevertheless, a proof-of-concept study in mice harboring various KRAS-mutant tumor xenografts showed that an anti-mutant KRAS antibody (RT11) in able to penetrate tumor cells and inhibit KRAS-mutated tumor-cell proliferation and disease progression." (PMID 30283732, 2018).
tumor (continued). "It has been recently reported that autophagy is an important mechanism for sustaining glycolytic RAS-mediated oncogenic transformation and KRAS oncogene upregulates basal autophagy to meet tumor cell survival in starvation and tumorigenesis." (PMID 29440631, 2018). "The usefulness of KRAS testing in CTCs before curative surgery was addressed in 35 mCRC cases at various tumor stages." (PMID 29441349, 2018). "To test the potential application of KYA1797K in humans, we established tumor organoids derived from CRC patient tissues harboring both APC (truncated form, Arg216*stop) and KRAS (Gly12Ser) mutations, which were identified by whole exome sequencing." (PMID 30459318, 2018). "These tumors regressed to baseline (compared to HBEC-iKRASG12D-GFP on Dox) thus indicating tumor growth dependence on activated KRAS, and transitioning animals back onto a Dox diet led to tumor re-development (purple line)." (PMID 30013058, 2018). "Even if responses were uncommon, the majority of tumor regression occurred in KRAS-mutant patients, with a stable disease as result." (PMID 29464099, 2018). "Yet, the KRAS mutant AF was low (3%) compared to the AF in the tumor itself (45% in AC and HGIN), leaving the positive predictive value of the test questionable." (PMID 29441349, 2018). "Loss of another tumor suppressor, the AMPK activator liver kinase B1 (LKB1), is prevalent in KRAS mutant tumors." (PMID 30159313, 2018). "ODC activity was found to be upregulated in KRAS mutant cancer cells and DFMO treatment prevented tumor formation in nude mice injected with KRAS activated tumors." (PMID 29419804, 2018). "The mutational status (KRAS and PIK3CA genes) of the primary tumour (T11) and its matched metastasis (M11) was confirmed by Sanger analysis." (PMID 29416628, 2018). "Contaminating normal epithelial cells were the predominant cell type in early passage cultures, although KRAS‐mutant tumor cells were cultured in one donor culture." (PMID 29569246, 2018). "The results of this study showed that KRAS and NRAS mutataions are usually present in the large majority of tumor cells, whereas BRAF and PIK3CA mutations often affect a limited, subclonal fraction of tumor cells." (PMID 29652830, 2018). "The majority of the tumor-associated KRAS mutations in CRC patients occur at codons 12, 13, and 61 of the KRAS gene." (PMID 29755662, 2018). "Collectively, these findings suggest that AZD2014, in combination with selumetinib, results in significant anti-tumor activity of RICTOR/KRAS-altered LUAD, through simultaneous blockade of mTORC1/2 and MEK pathways." (PMID 30338041, 2018). "Evidence using cancer cell lines has indicated that KRAS antisense oligodeoxynucleotide inhibits KRAS expression, tumor growth, and tumor invasiveness, and that the oligodeoxynucleotide can also suppress peritoneal dissemination of cancer cells in vivo." (PMID 29682203, 2018). "Advanced individual therapy concepts focus on well characterized mutations, e.g. KRAS and BRAF, and thus stress the understanding of tumor biologies for individualized medicine." (PMID 28903393, 2017). "CRIS-D groups a subset of tumours enriched for IGF2 overexpression, which has been recently implicated in desensitization to EGFR blockade in patients with KRAS wild-type tumours." (PMID 28561063, 2017). "Only a trend was observed for mutant KRAS tumours that exhibited a slightly worse median PFS for mFOLFOX6 compared with mFOLFOX6 plus aflibercep regimen." (PMID 28708103, 2017). "Conversely, CRIS-A comprises BRAF-mutant MSI tumours but also KRAS-mutant MSS samples with MSI-like features, and overall has distinctive metabolic features." (PMID 28561063, 2017).
tumor (continued). "This accounted for 38/351 patients (10.8%) in the prospective cohort (37 CRC patients with activating KRAS or NRAS mutations and one GIST patient with a PDGFRA D842V mutation) and is also an important outcome of tumour testing." (PMID 28196074, 2017). "We harvested RNA from FG (KRasG12D mutant) and BxPC3 (KRas wild type) PDAC cells grown in vitro or as in vivo xenografts using our mH-based extraction method of RNA from the FFPE tumor samples." (PMID 27602776, 2017). "Pleural disseminated, mutant KRAS bearing tumour cells upregulate and systemically release chemokine ligand 2 (CCL2) into the bloodstream to mobilize myeloid cells from the host bone marrow to the pleural space via the spleen." (PMID 28508873, 2017). "Research has also focused on the alterations that involve the TCA cycle and mutant KRAS-induced tumor cell dependencies for glucose, glutamine, and extracellular protein." (PMID 28298227, 2017). "Despite a previous conception that KRAS and BRAF mutations are mutually exclusive, we found 1 dual BRAFV600E+KRASA164V^submutated tumor that, in our case, was associated with poor prognostic features." (PMID 28178681, 2017). "The first blinded prospective multicenter study compared the mutation status of KRAS and BRAF in CRC tumor tissue, using routine gold-standard methods, and in ctDNA, using a quantitative PCR-based method." (PMID 28903450, 2017). "Using the TST vendor-supplied bioinformatics pipeline we were able to detect and validate by orthogonal methods known activating driver mutations in EGFR, KRAS and BRAF below 5% VAF in cases with ≥10% tumor cell content by routine pathological assessment." (PMID 28415793, 2017). "Past studies pointed to the anti-tumour function of miR-217 in several cancers, including the targeting of the KRAS oncogene in PDAC." (PMID 29050264, 2017). "This rich data set offers an opportunity to examine the likelihood KRAS mutations confer acquired resistance to an anti-EGFR antibody and provided a platform to examine variables affecting tumor-doubling times." (PMID 28981524, 2017). "In patients with sequencing data from matched samples, the concordance between the primary tumour and the PM for KRAS, NRAS and BRAF was 93% (14/15), 100% (15/15) and 100% (14/14 patients) respectively." (PMID 29029407, 2017). "Of the 40 KRAS G12C tumors examined for tumor-derived HLA neoantigen prediction, eight were HLA-A*11:01." (PMID 28231819, 2017). "Although currently published (pre-)clinical data report contradictory results, KRAS and PIK3CA mutation status have previously been associated with respectively resistance and sensitivity to mTOR inhibition in particular tumor types." (PMID 28903445, 2017). "In one patient (Patient IX), we found discordant results between the KRAS status of single CTCs and the primary tumor." (PMID 28468669, 2017). "Targeted NGS analyses showed the same KRAS and SMAD4 mutations in both the tumour of the upper lobe and one of the tumours in the lower lobe." (PMID 28347348, 2017). "Somatic KRAS analysis on tumor tissue has been suggested as a prescreening test to further select patients with CRC for germline genetic testing, particularly in those with atypical presentation (CRCs with no or few polyps)." (PMID 29147111, 2017). "For evaluation of EGFR and KRAS mutations we used tissue adjacent to the implants, LLC cells in culture and tumor implants." (PMID 29285236, 2017). "In this study we demonstrated that tumors from the LLC cells present KRAS mutation with tumor overexpression of VEGF, EGFR and KRAS." (PMID 29285236, 2017). "Patients with KRAS wild-type tumors and liver metastases in this cohort had relatively unfavorable factors, such as a high tumor burden or multiple organ metastases, and patients with relatively favorable factors were usually excluded." (PMID 28068936, 2017). "To uncover a core of genes consistently regulated by KRAS across mouse and human tumours, we followed a two-tiered approach." (PMID 28220783, 2017).